S100A9 (S100 calcium binding protein A9)
Diseases named in the same sentence as S100A9 in open-access papers (continued):
Sharing a sentence is not in itself a finding about the gene and the disease.
tumor (continued). "By releasing angiogenic factors including S100A8 and S100A9, as well as activating vascular endothelial growth factors A (VEGFA) in the extracellular matrix and MMP9, tumor angiogenesis was maintained by neutrophils." (PMID 36609243, 2023). "Two weeks after tumor inoculation, BM from DP42-bearing mice had a significantly higher amount of S100A8/S100A9 than tumor-free mice." (PMID 36923707, 2023). "First, S100A8/S100A9 promotes tumor cell growth through the activation of the NF-κB signaling pathway in a RAGE-dependent manner, while S100A8/S100A9 can interact with RAGE." (PMID 37346040, 2023). "HCC tumor tissues contain high levels of HMOX1, S100A9, TMC7, TRAF3 and TRIM21, whereas the expression of IL8RAP and RGL4 were higher in the control group." (PMID 37171396, 2023). "There is a possibility that in tumor-free mice, S100A8/S100A9 exist mainly in the form of tetramers and that TQ is unable to bind S100A9 and block its effects." (PMID 36923707, 2023). "Studies have shown that myeloid cell-derived S100A9 can increase blood supply and promote angiogenesis by inducing IL6 and IL10 to create a survival niche for subsequent tumor progression in multiple myeloma." (PMID 37701037, 2023). "Tumor-infiltrating CD68 Tams were analyzed and compared with blood S100A9 MDSCs from the same patients." (PMID 36817434, 2023). "In particular, the mRNA levels of Lyz2 and S100a9, 2 top downregulated genes in CD8+ T cells from syngenic MC38 tumor in KO mice, were dramatically induced in OT-I CD8+ T cells cocultured with WT DCs loaded with the apoptotic MC38-OVA." (PMID 37581941, 2023). "Further studies are required to fully understand these opposing roles of S100A9 in AML pathogenesis and tumor progression." (PMID 38110349, 2023). "MG and tumor tissues than in WTMG and WT tumor tissues were further confirmed by immunohistochemistry (IHC) with antibodies against S100a8 and S100a9, which are the markers for MDSCs." (PMID 35304461, 2022). "The Hub gene was identified and constructed based on 6 genes (KLRB1, KLF2, S100A9,MSC,ANXA5 and IMPDH1), which will help to for a predictive analysis of the tumor immune microenvironment in HCC patients." (PMID 35992798, 2022). "Tumor-infiltrating monocytes/macrophages increase tumor invasion and migration by increasing the expression of S100A8 and S100A9 in cancer cells." (PMID 35646116, 2022). "Consistently, treatment with a chemical inhibitor of S100A9 or CXCL12 also significantly inhibited MDSC accumulation and slowed down tumor growth." (PMID 35304461, 2022). "The Calprotectin subunits S100A8 and S100A9 as well as the receptor CD147 were elevated expressed in PeCa compared to non-malignant tissue, with a markedly higher expression at the tumor core and lymph node metastases." (PMID 36303837, 2022). "Peptibodies significantly delayed tumor growth in EL4 mice and alarmins S100A8/S100A9 were identified as potential candidate targets expressed by the MDSC." (PMID 36304465, 2022). "S100A9 and PGAM5 expression was significantly upregulated in tumor tissues compared with normal liver tissues." (PMID 36041055, 2022). "TAMs and CAFs were classified according to their tumor origin and high expression of SPP1, C1QB, IL1B, S100A8, S100A9 and type I collagens (COL1A1 and COL1A2)." (PMID 36209225, 2022). "The S100 protein family members, S100A8A/S100A9, which form an S100A8/A9 heterodimeric complex able to interact with both TLR4 and RAGE on tumor cells, are also key in promoting RAGE-mediated inflammatory responses." (PMID 35727208, 2022). "Mechanistically, MDSC-derived exosomal S100A9 increased circMID1 expression to sponge miR-506-3p, leading to increased MID1 expression and accelerated tumor progression." (PMID 35918733, 2022).
tumor (continued). "In contrast to the presumed specificity of S100B, a variety of tumours and cells originating from all germ layers can be induced to express S100 proteins, particularly S100A8, S100A9, S100A12 and S100B, as a result of oxidative stress and tissue inflammation." (PMID 35323240, 2022). "In fact, MDSCs-shed Exos contain proinflammatory mediators such as S100A9 and S100A8, which promote tumor progression and suppress anti-tumor responses." (PMID 35918733, 2022). "The non-invasive in vivo imaging of S100A9, as described here, reflects the local activity of the TME during tumor development as well as changes under treatment." (PMID 33401528, 2021). "One important impact of S100A8 and S100A9 proteins on leukemic cells is also mediated through their action on the recruitment of myeloid derived suppressor cells (MDSC), which promote tumor progression and establish a favorable pro-tumoral niche." (PMID 33801279, 2021). "We found that S100A9, an immunosuppressive molecule, was much higher in NKTCL patients both in serum and tumor stroma." (PMID 34045609, 2021). "The link between tumor infiltrating monocytes/macrophages and S100A8 and S100A9 expression in cancer cells supports their role in diffusion and spreading of cancer cells." (PMID 33801279, 2021). "S100A8/9 dimers were reported to promote tumor cell proliferation by creating a pro-inflammatory microenvironment and contribute to disease progression in MPN, whereas tasquinimod, an S100A8/S100A9 inhibitor, inhibited the MPN phenotype." (PMID 34390367, 2021). "Further, STAT-3 has been identified as a crucial regulator of MDSC expansion that conveys the recruitment of MDSC to the tumor site by upregulating the pro-inflammatory S100A8 and S100A9 proteins." (PMID 33430105, 2021). "Compared to non-tumor-bearing fatpads, mouse mammary epithelial cells and peritumoral stromal cells showed increased expression of both S100A8 and S100A9." (PMID 33446797, 2021). "Recently, S100A9 and S100A8 have been used to develop an attractive tool for the depletion of MDSCs in tumor-bearing mice." (PMID 34201758, 2021). "One established downstream mediator of S100A8/S100A9 signaling is MAPK, which upon phosphorylation can induce tumor cell migration; this is of particular interest because S100A8 is a chemotactic agent." (PMID 34975408, 2021). "S100A9‐targeted CPMV particles were tested as a potential immunotherapy against B16F10 and 4T1‐Luc mice tumor models." (PMID 34519180, 2021). "Neutralizing anti-S100A8 and anti-S100A9 antibodies blocked the morphological changes and migration of CD11b/CD18 positive myeloid cells into the lungs of tumor-bearing mice through p38 signaling." (PMID 34201758, 2021). "It has been reported that tumor-infiltrating monocytes promoted invasion and migration of tumor cell via up-regulating S100A8 and S100A9 expression." (PMID 33758602, 2021). "CRC patients with a low number of infiltrating CD8+ T cells into tumor tissues expressed high levels of both CCL5 and S100a9." (PMID 32630699, 2020). "In silico pathway analysis followed by candidate-based RNA interference mediated loss-of-function analysis revealed a critical role of S100A8, S100A9, and LGALS3BP as molecular determinants of TIC proliferation, migration, and in vivo tumor growth." (PMID 32503348, 2020). "Marking the same healthy stroma (ROI1) vs. tumor (ROI2) areas as for S100A8 and S100A9 analysis, lipid expression was displayed in a gel view format in the 400–1000 Da MW range." (PMID 32733643, 2020). "The xenografted cells multiplied in a time-dependent manner, and tumor volume and weight were observed to decrease after administration of S100A8 and S100A9." (PMID 32903598, 2020). "Since appropriate function of granulosa cells is critical for normal follicular development, we selected the most widely used granulosa‐like tumour cell lines, KGN cells, to explore the effect of S100‐A9 on its functions." (PMID 31568644, 2020).
tumor (continued). "This is likely due to the decreased secretion by TAMs of S100a9, a calcium-binding protein considered a pro-inflammatory mediator involved in CD8+ T cell migration into the low hypoxic area of tumor tissues." (PMID 32630699, 2020). "Growing studies have verified that heterocomplex of S100A8/S100A9 led to MDSC migration and mediated tumor cell invasion." (PMID 33117687, 2020). "The delay in tumor engraftment due to perturbation of S100A8 and S100A9 further corroborates our experimental findings and suggests a prominent role of these two proteins regarding cancer stemness in pancreatic TICs." (PMID 32503348, 2020). "Comparing the tumor to the healthy epithelium, the expression level of S100A8 and S100A9 in the tumor appeared slightly higher, which was found statistically significant." (PMID 32733643, 2020). "Tumor-derived TGF-β, together with other factors, such as VEGFA and TNFα, stimulates the release of chemoattractants, such as S100A8 and S100A9, that mediate the recruitment of immune cells in the pre-metastatic niche." (PMID 32397392, 2020). "Many upregulated genes in the heat map have been reported to promote tumor metastasis, such as FOSB, OLR1, S100A9, MMP9, and ANGPTL4 36-40." (PMID 31598162, 2019). "The levels of exosomal S100A9 were higher in CRC patients, and tumor relapse patients exhibit levels higher than those in successful CRC resection patients." (PMID 31559140, 2019). "Serum protein levels and tumor transcript levels of S100A8 and S100A9 were used for detailed analysis to probe the role of these two proteins in GBM diagnosis and prognosis." (PMID 30808902, 2019). "It is worth noting that both serum S100A9 and TNC levels exhibit a significant increase in CRC patients with tumor metastasis (p=0.025; p=0.085)." (PMID 31632476, 2019). "Consistent with RNA-seq results, western blot analysis confirmed the increased expression of S100A9 and decreased expression of APOBEC2 in tumours induced by both routes of infections." (PMID 31340720, 2019). "In the 4T1 mammary and LLC lung carcinoma models, enhanced expression of pro-metastatic proteins in MDSCs, such as Bv8, MMP9, S100A8 and S100A9, facilitates improved PMN formation, which supports more efficient tumor cell extravasation and proliferation." (PMID 30792719, 2019). "Monocytes, known for their functional and molecular plasticity, can be recruited to the tumor site by tumor‐secreted chemo‐attractants (eg, CCL2, S100A8/S100A9), and polarized toward M1 or M2 macrophages depending on the cytokine milieu." (PMID 31033233, 2019). "Induction of S100A8 and S100A9 expression in response to primary lung tumor cell-derived soluble factors VEGF-A, TGF-β and TNF-α in myeloid cells prior to tumor metastasis has been reported." (PMID 30558665, 2018). "In our study, we showed that monocytic S100A9+ MDSCs is well correlated to tumor infiltrating TAMs, and that NSCLC MDMs retained S100A9 and phenotypically had the M2 marker CD206." (PMID 29484139, 2018). "In tumor tissue, we were able to show CD68/S100A9 double stained TAMs, suggesting their S100A9+ MDSC origin." (PMID 29484139, 2018). "We further found that percentages of blood S100A9+ MDSCs were well correlated with counts of S100A9+ cells and CD68 TAMs in tumor tissues." (PMID 29484139, 2018). "The tumor growth rate and hepatic metastasis of CCL5−/− mice were increased after S100a9 treatment compared to CCL5−/− mice treated with PBS." (PMID 29991744, 2018). "These neutrophils contribute to the elevated levels of pro-metastatic molecules like S100A8, S100A9, Bv8, and MMP9 in the lungs, supporting tumor cell homing to this organ." (PMID 29340117, 2017). "Hiratsuka and colleagues showed that primary tumor cells release VEGF-A, TGFβ and TNFα that in turn, induces the expression of the chemoattractants such as S100A8 and S100A9 by lung endothelium and myeloid cells." (PMID 29340117, 2017).
tumor (continued). "TGF-β signaling is also a significant contributor in the metastatic environment through regulation of chemo-attractants S100A8, S100A9, and ANGPTL4, which enhance tumor cell invasion and disruption of vascular endothelial cell-cell junctions." (PMID 27223426, 2017). "It has been reported that S100A9 not only induce the accumulation of MDSC, but it is also secreted by MDSC and tumor cells, and bind to cell surface receptors (such as RAGE) leading to MDSC migration." (PMID 27020242, 2016). "To verify this impression, we compared the area of the invasion front of each individual tumor colony and found the invasive areas to be significantly reduced when S100A8 and S100A9 were downregulated in both MC38 and LLC cells." (PMID 27086923, 2016). "On examination of the hematoxylin- and eosin-stained liver sections, tumor colonies appeared to be better demarcated, with well-circumscribed borders in the S100A8 and S100A9 knockdown groups compared with controls." (PMID 27086923, 2016). "So the autocrine feedback loop is created between S100A9 and MDSC that have significant influence on the inflammatory tumor environment." (PMID 27020242, 2016). "We demonstrate that tumor-infiltrating monocytes/macrophages induced S100A8 and S100A9 expression in cancer cells to promote migration and invasion." (PMID 27086923, 2016). "S100A8 forms heterocomplexes with S100A9.34, 35 Downregulation of either S100A8 or S100A9 in cancer cells reduced tumor migration and invasion." (PMID 27086923, 2016). "Pro-tumor neutrophils upregulate the expression of pro-metastatic proteins, e.g., Bv8, S100A8, and S100A9, but also VEGF and MMP9 in pre-metastatic lungs of IFN-deficient mice." (PMID 28066438, 2016). "Since expression levels appeared unaffected by the tumor stage, suppression of S100A8 and S100A9 expression is likely an early event in the pathogenesis of HNSCC and is independent of HPV status and copy number gains." (PMID 26883112, 2016). "Comparison of tumor colonizes of different sizes in the three experimental groups also showed markedly reduced invasive areas in the S100A8 and S100A9 knockdown groups." (PMID 27086923, 2016). "In this study, we show that tumor-infiltrating monocytes/macrophages regulate the expression of S100A8 and S100A9 in cancer cells." (PMID 27086923, 2016). "Staining area and intensity of MMP2 and MMP9 in the MC38 and LLC tumor colonies were notably decreased in the S100A8 and S100A9 knockdown groups compared with controls." (PMID 27086923, 2016). "In our model, tumor-derived S100A8 and S100A9 have distinct effects apart from myeloid cell recruitment, one of which is to promote cancer cell invasion." (PMID 27086923, 2016). "Neutrophils accumulating in pre-metastatic lungs support tumor cell extravasation and proliferation by release of pro-metastatic proteins, e.g., Bv8, MMP9, S100A8, and S100A9." (PMID 28066438, 2016). "S100A9 present in neutrophils and other myeloid cells has been reported to be expressed in human CRC and to coincide with tumor progression and invasion." (PMID 27344176, 2016). "The mean tumor weight, the percentage of proliferating Ki67-positive nuclei, and CD31-positive microvessel numbers were significantly increased in S100A9 tumor tissues relative to vector ones at the ending point." (PMID 26315114, 2015). "These genes included tumor markers (MUC16), genes that control tumor migration (MYL9), metastasis (CEACAM6, VEGFC, CX3CL1, CST1, CCL5, S100A9, IGF1, NOTCH3), cell adhesion (FN1, CEACAM1), and inflammation (TRAF2, NF-κB2 and RelB)." (PMID 26090868, 2015). "The comparisons of S100A8 and S100A9 genes in normal control and different RCC tumor T stages indicated that with T stage progression, the upregulation of S100A8 and S100A9 genes increased." (PMID 25673070, 2015). "Such tumor angiogenesis requires HDAC4 and S100A9 dependent signaling in the cancer cells themselves as well as in the infiltrating host cells." (PMID 25193858, 2014).
tumor (continued). "We therefore studied the effects of S100A8, S100A9 and the S100A8/A9 complex, but also of NT-S100A8, on critical aspects of tumor biology, namely intracellular signaling, cell proliferation and EMT." (PMID 24670043, 2014). "We conclude from these data that a chemical probe selected only for its ability to bind S100A9 and inhibit its interaction with TLR4 and RAGE, show anti-tumor activity in vivo." (PMID 23667563, 2013). "We show here that OX, which has a very similar effect on S100A9-RAGE/TLR4 interactions as Q compounds, also shows anti-tumor effect in vivo in the same tumor model." (PMID 23667563, 2013). "On the other hand, it has been observed that S100A9 homodimers interacted with TLR4 and RAGE, which are two receptors involved in the control of tumour growth in different systems." (PMID 23626736, 2013). "Factors produced by the primary tumor such as VEGF-A, TNFα, and TGFβ also induce expression of the pro-inflammatory cytokines S100A8 and S100A9 in developing pre-metastatic niches in the lung." (PMID 22699312, 2012). "This conclusion was supported by the finding that ABR-215050, a small molecule inhibitor of the S100A9/TLR4 interaction, significantly inhibited EL4 tumor growth." (PMID 23234398, 2012). "The S100A8 and S100A9 proteins are RAGE ligands, DAMPs, markers of myeloid-derived suppressor cells, GM-CSF induced cytokines in eosinophils, and tumor promoting factors in experimental models." (PMID 22251275, 2012). "S100A8, a calcium-binding protein that complexes with S100A9 and whose expression is suppressed by functional BRCA1, is induced by H-Ras to promote malignant potential (tumor cell invasion and migration)." (PMID 21627793, 2011). "Because S100A9 and S100A11 showed a strong involvement in the aggressiveness of GBM and could have a direct effect on RAGE, the effect of Azeliragon on GBM tumor tissue was examined." (PMID 39744679, 2025). "This over-expression may result from MØ-derived S100A9 contributing to the tumor microenvironment (TME), where it promotes chronic inflammation that facilitates tumor growth and metastasis." (PMID 40565156, 2025). "Additionally, CSC markers ADM, DLGAP5, S100A9, and TNFRSF11B showed consistent overexpression at both RNA and protein levels in tumor samples, with significantly lower expression in normal tissues." (PMID 40243557, 2025). "Furthermore, NMIIA, S100A9, and HSPB1 upregulation in cancer has been correlated with the resistance of the targeted tumor to chemo‐, radio‐, and/or immunotherapy." (PMID 40138733, 2025). "Concurrently, BC cells secrete factors like ERH, RPA2, and S100A9, which are not normally present in the brain, thereby enhancing tumor proliferation." (PMID 39712454, 2025). "Since S100A9 inhibition alone using tasquinimod is not sufficient to eliminate tumors despite reduced tumor growth and metastasis in vivo, we next evaluated the ability of tasquinimod to sensitize tumors to cisplatin chemotherapy." (PMID 41173834, 2025). "VEGF and TGF-β1 capture essential aspects of tumor angiogenesis, hypoxia signaling, and stromal remodeling, whereas danger signals such as HSP90, HMGB1 and S100A9 report on cellular stress, necrosis, and innate immune activation that shape the tumor microenvironment." (PMID 41009692, 2025). "In a variety of tumors, S100A9 forms a heterodimer with S100A8, S100A8/A9, which interferes with the tumor microenvironment and metabolism, promotes tumorigenesis, progression and metastasis, and serves as a tumor diagnostic and prognostic marker as well as a potential therapeutic target." (PMID 40630623, 2025). "While S100A9, IL-10, and Cxcl2 expression was reduced in a-PD-L1-treated 2F8c tumors compared to tumor controls, no reduction was detected between a-PD-L1-treated and control Egfl6+ tumors." (PMID 39312740, 2024). "For both the in vivo tumor challenge experiment and the in vitro migration assay, we utilized recombinant S100A9 protein and not S100A8 or heterodimeric S100A8/A9." (PMID 39497822, 2024).